Y_RNA (Y RNA )
Gene: Miscellaneous RNA gene on chromosome 15 (48,325,558 to 48,325,671, reverse strand). Ensembl gene ENSG00000202542.
Homologues: Orthologues: chimpanzee Y_RNA (100% identical), macaque Y_RNA (95% identical), dog Y_RNA (74% identical). Paralogues in human: Y_RNA (80% identical), Y_RNA (79% identical), RNY1 (77% identical), Y_RNA (77% identical), Y_RNA (75% identical), RNY1P5 (74% identical), Y_RNA (74% identical), Y_RNA (73% identical), Y_RNA (72% identical), RNY1P11 (71% identical), Y_RNA (71% identical), RNY1P7 (70% identical), and 88 more.